SACK1G (scaffolding CK1 anchoring protein G)
Description:
Substrate for type I BMP receptor kinase involved in regulation of some target genes of the BMP signaling pathway. Also regulates the expression of several non-BMP target genes, suggesting a role in other signaling pathways.
Synonyms: FAM83G; PAWS1; FLJ41564
Tractability: PROTAC: ubiquitination databases record sites on it.
Gene: Protein-coding gene on chromosome 17 (18,968,789 to 19,004,815, reverse strand). Ensembl gene ENSG00000188522.
Subcellular location: Cytoplasm, cytosol; Nucleus
Subcellular location (Human Protein Atlas): Cytosol
Gene Ontology:
Molecular function: protein binding; protein kinase binding
Biological process: BMP signaling pathway
Cellular component: cytosol; nucleus
Genetic constraint (gnomAD): Loss-of-function variants: 37 observed, 56.49 expected, observed/expected ratio (o/e) 0.66, 90% interval 0.5 to 0.86. The upper end of that interval is the gene's LOEUF score, 0.86, which puts it in group 3 of 6, group 1 being the genes least tolerant of losing a copy. Missense variants: 938 observed, 1,089.7 expected, observed/expected ratio (o/e) 0.86, 90% interval 0.81 to 0.91. Synonymous variants: 445 observed, 457.25 expected, observed/expected ratio (o/e) 0.97, 90% interval 0.9 to 1.05.
Homologues: Orthologues: chimpanzee FAM83G (99% identical), macaque FAM83G (95% identical), dog FAM83G (83% identical), pig FAM83G (82% identical), guinea pig FAM83G (81% identical), mouse Fam83g (80% identical), rat Fam83g (80% identical), rabbit FAM83G (78% identical), tropical clawed frog fam83g (51% identical), zebrafish fam83gb (35% identical), zebrafish fam83ga (34% identical). Paralogues in human: SACK1F (21% identical), SACK1H (20% identical), SACK1E (19% identical), SACK1B (19% identical), SACK1C (18% identical), SACK1D (18% identical), SACK1A (15% identical).
Diseases named in the same sentence as SACK1G in open-access papers:
SACK1G is named in the same sentence as 12 diseases in open-access papers, as found by Europe PMC text mining. Sharing a sentence is not in itself a finding about the gene and the disease.
SACK1G shares sentences with these, for which no sentence is quoted: cancer (10 papers); osteosarcoma (5); Palmoplantar keratoderma (5); breast carcinoma (2); hepatocellular carcinoma (2); prostate carcinoma (2); tumor (2); gastric cancer (1); Hyperkeratosis (1); lung carcinoma (1); lymph node metastasis (1); small cell lung carcinoma (1).